PTGR3 (prostaglandin reductase 3)
Description:
Functions as 15-oxo-prostaglandin 13-reductase and acts on 15-keto-PGE1, 15-keto-PGE2, 15-keto-PGE1-alpha and 15-keto-PGE2-alpha with highest efficiency towards 15-keto-PGE2-alpha. Overexpression represses transcriptional activity of PPARG and inhibits adipocyte differentiation.
Synonyms: PRG-3; ZADH2; MGC45594; PTGR-3
Tractability: Small molecule: a structure with a bound ligand is known. PROTAC: ubiquitination databases record sites on it.
Gene: Protein-coding gene on chromosome 18 (75,195,113 to 75,209,139, reverse strand). Ensembl gene ENSG00000180011.
Subcellular location: Peroxisome
Subcellular location (Human Protein Atlas): Vesicles; Golgi apparatus; Nucleoplasm
Gene Ontology:
Molecular function: 15-oxoprostaglandin 13-reductase [NAD(P)+] activity; oxidoreductase activity; zinc ion binding
Biological process: negative regulation of fat cell differentiation; prostaglandin metabolic process
Cellular component: mitochondrion; peroxisome
Genetic constraint (gnomAD): Loss-of-function variants: 16 observed, 20.83 expected, observed/expected ratio (o/e) 0.77, 90% interval 0.52 to 1.17. The upper end of that interval is the gene's LOEUF score, 1.17, which puts it in group 5 of 6, group 1 being the genes least tolerant of losing a copy. Missense variants: 507 observed, 479.54 expected, observed/expected ratio (o/e) 1.06, 90% interval 0.98 to 1.14. Synonymous variants: 210 observed, 192.55 expected, observed/expected ratio (o/e) 1.09, 90% interval 0.97 to 1.22.
Homologues: Orthologues: chimpanzee PTGR3 (99% identical), macaque PTGR3 (97% identical), dog PTGR3 (90% identical), rat Ptgr3 (89% identical), mouse Ptgr3 (88% identical), pig PTGR3 (87% identical), rabbit PTGR3 (85% identical), guinea pig PTGR3 (76% identical), tropical clawed frog ptgr3 (75% identical), Drosophila melanogaster CG4836 (28% identical), Caenorhabditis elegans D2063.1 (19% identical), Caenorhabditis elegans adh-1 (18% identical), and 1 more. Paralogues in human: VAT1 (27% identical), VAT1L (26% identical), TP53I3 (21% identical), MECR (20% identical), PTGR2 (20% identical), RTN4IP1 (19% identical), CRYZ (19% identical), PTGR1 (19% identical), ADH1B (18% identical), ADH1C (18% identical), ADH5 (18% identical), SORD (18% identical), and 5 more.
Diseases named in the same sentence as PTGR3 in open-access papers:
PTGR3 is named in the same sentence as 7 diseases in open-access papers, as found by Europe PMC text mining. Sharing a sentence is not in itself a finding about the gene and the disease. The quoted sentences say what the papers report.
colorectal cancer (1 paper, 2025). A primary or metastatic malignant neoplasm that affects the colon or rectum. "The PTGR3 gene (phosphatase of regenerating liver-3, or PRL-3) correlates significantly with tumor progression and patient outcomes in colorectal cancer (CRC)." (PMID 40650042, 2025).
Glucose intolerance (1 paper, 2025). Glucose intolerance (GI) can be defined as dysglycemia that comprises both prediabetes and diabetes. "We also found that Ptgr3 knockout mice displayed markedly improve insulin sensitivity and glucose intolerance (unpublished data)." (PMID 40119175, 2025).
PTGR3 also shares sentences with these, for which no sentence is quoted: Alzheimer disease (1 paper); dementia (1); immune disorders (1); schizophrenia (1); tumor (1).